SPP1 (secreted phosphoprotein 1)
Diseases named in the same sentence as SPP1 in open-access papers (continued):
Sharing a sentence is not in itself a finding about the gene and the disease.
tumor (continued). "Other significant DE genes with high FC(log2), unique to the study were INHBA, COL1A1, COL11A1, COMP, SFRP4 and SPP1, which were clustered in STRING network analysis and correlated with tumour-infiltrating immune cells in TIMER, suggesting a specific interaction pathway." (PMID 34824625, 2021). "Indeed, TAMs show high levels of gene expression enriched in the pathways which promote cell migration, angiogenesis, tumor progression, and inflammation (e.g., APOE and SPP1)." (PMID 33144684, 2021). "SPP1 expression was significantly higher in tumor tissues than in adjacent tissues, regardless of RNA or protein level (P < 0.001)." (PMID 34178613, 2021). "Previous epigenetic studies emphasized the relationships between methylation of the promoters of SSP1 and S100A6 and expression of these genes, but few studies examined the relationship of SPP1 and S100A6 expression with global methylation levels of tumor cells." (PMID 34857857, 2021). "Further analysis of the correlation of the expression level of the prognostic genes with age, gender, tumor stage and tumor grade of HCC patients showed that the expression of FYN, PPP1CC, RAC1, and SPP1 was significantly correlated with the tumor grade (P < 0.05)." (PMID 33850056, 2021). "Moreover, SPP1 induces increased PLAU production that indirectly activates MMP1, which promotes tumor progression and LSCC cell migration and invasion." (PMID 33092550, 2020). "The group of tumours from patients with recurrence (n = 25) expressed higher levels of SPP1 (p = 0.003) than non-recurrence tumours (n = 75)." (PMID 31996744, 2020). "In fact, CXCR4, SPP1, ACKR3, CCL2, PTGS2, CD274 (PD-L1), CXCL11 were upregulated while CCL28, CCR1, CCR7 were down regulated in both comparisons (blue boxes), suggesting this as a signature specific of the core region of the tumor." (PMID 33066172, 2020). "Upregulation of SPP1 promoted CRC cell proliferation in vitro and tumor growth in vivo." (PMID 33294000, 2020). "Remarkably, almost no cases showed local invasion in which the tumours expressed no OCT4 or SPP1 transcripts (gene score: 0; 1/9)." (PMID 32503462, 2020). "Many components of this family such as periostin (POSTN), osteopontin (SPP1), or the CNN family of proteins have been shown to regulate key aspect of tumor biology, including proliferation, invasion, matrix remodeling, and dissemination to pre-metastatic niches in distant organs." (PMID 29946533, 2018). "Tumor and stromal cells generate the extracellular matrix (ECM), which comprises structural proteins and proteins that regulate cell function and their interactions, such as osteopontin (OPN, SPP1) and other matricellular proteins." (PMID 28193231, 2017). "Moreover, the CM-FLF-induced apoptosis resistance or chemotaxis of tumor cells was attenuated when ITGAV, the common receptor of FN1 and SPP1, was silenced by RNA interference or blocked by GRGDS treatment in tumor cells." (PMID 27329720, 2016). "Overall, these findings imply that blockade of the FN1/SPP1-ITGAV pathway may inhibit the seeding and consequently the metastasis of tumor cells in fibrotic lungs." (PMID 27329720, 2016). "Collectively, we suggest that fibrotic microenvironment may enhance the metastatic seeding of tumor cells in the lung by chemoattracting tumor cells and inhibiting their apoptosis via activating the FN1/SPP1-ITGAV signaling." (PMID 27329720, 2016). "Furthermore, the serum deprivation-triggered apoptosis was increased when tumor cells were cultured in the conditioned medium from the FN1 and SPP1-silencing fibroblasts, and this effect was more prominent when both FN1 and SPP1 were silenced in fibroblasts." (PMID 27329720, 2016). "We selected five genes, SPP1, COL1A1, NT5E, HTRA1 and ANGPT1, of 15 genes whose coding proteins could be secreted from the pituitary, and we examined their tumor expression in 118 CD patients." (PMID 27690016, 2016).
tumor (continued). "Eight of these immune response genes (SPP1, PDPN, IL1RN, IL6, CCL8, MDK, IRF7, and HRH4) were expressed between 1.25–1.59 fold higher in the microglia/macrophage enriched population compared to bulk tumor." (PMID 22937035, 2012). "Both univariate and multivariate analyses identified stage (p<0.0001) and LEF1 overexpression (p<0.05) as important prognostic markers, but not tumor grade or SPP1." (PMID 21383983, 2011). "High expression of SPP1 in tumour samples but not in cell lines suggests that this gene is mostly expressed by stromal cells and other infiltrating cells within tumours but not by ESFT-cells themselves." (PMID 22084725, 2011). "The SPP1 gene (osteopontin) is a non-collagenous bone matrix protein with several functions, such as bone remodeling, angiogenesis, cell adhesion, tumor migration and invasion." (PMID 17022822, 2006). "Considering SPP1+ VSIG4− TAMs also possessed strong activity of neutrophil chemotaxis, we then explored whether simultaneously inhibiting VSIG4 and SPP1 could improve the anti-tumor effect against ATC." (PMID 39920772, 2025). "Additionally, SPP1 plays a role in mediating interactions between macrophages and epithelial cells by regulating inflammation, epithelial-mesenchymal transition (EMT), immune evasion, and metabolism, thereby contributing to tumor progression." (PMID 41384115, 2025). "Beyond their interactions with T‐cells and fibroblasts, SPP1+ TAMs expressing angiogenic, matrix remodelling, and immunosuppressive markers like Nlrp3, Tnf, Vegfa, and Arg1, also engage in cross‐talk with enteric glial cells via IL1R/IL6 signalling, further influencing tumour behaviour." (PMID 40395129, 2025). "Macrophages interacted with nearly all immune cell types specifically exhausted CD8+ T cells (CD8+ Tex) CD8+ Teff, CD4+ Treg 1 and Th17 by SPP1–CD44 interaction, which only occurred in tumour sites, and no expression of SPP1 in macrophages from normal bowel tissue and adenoma was observed." (PMID 39934971, 2025). "While increased expression of ECM-related genes like COL3A1, PLAU, and SPP1 may initially contribute to tumor growth, invasion, and metastasis by promoting ECM remodeling and cell migration, their downregulation later in tumor progression might reflect a more aggressive, metastatic phenotype." (PMID 41465316, 2025). "These cells co-localize in hypoxic tumor regions and are predicted to engage in direct adhesive interactions (e.g., COL1A1-ITGB1) and paracrine signaling via TGF-β, WNT5A-FZD2, and CCL3-CCR5 axes, promoting recruitment and pro-inflammatory activity of SPP1+ macrophages." (PMID 41450739, 2025). "Anti-CSF1R therapy may not be sufficient to deplete all tumor-promoting SPP1+ macrophages, which may contribute to the poor efficacy of anti-CSF1R monotherapy in the Renca mouse tumor model and human cancer patients." (PMID 40092488, 2025). "Furthermore, SPP1+ TAMs in PHT demonstrate enhanced angiogenic ability and inhibit lymphocyte migration, supporting their role in promoting tumor progression." (PMID 41028931, 2025). "iCAFs are enriched at the liver site and the tumor-liver interface, ECM CAFs with C1QC+ and inflammatory IL1B+ macrophages at the tumor-liver border and in the tumor site, whereas myofibroblasts and immunosuppressive SPP1+ macrophages infiltrate the tumor core." (PMID 40393458, 2025). "In addition, it is noteworthy that SPP1 does not universally exert tumor-promoting effects across all malignancies." (PMID 41391064, 2025). "SPP1 might induce resistance to the EGFR‐TKI, and influence tumor immune infiltration." (PMID 41498045, 2025). "Interestingly, the PECAM1/SPP1 correlation analysis indicates that healthy lung tissues are mostly PECAM1highSPP1,low while tumor samples appear PECAM1lowSPP1high (data not shown)." (PMID 40028673, 2025).
tumor (continued). "In addition, TRPM2-AS plays a vital role in regulating the tumor immune microenvironment of EC, overexpression of TRPM2-AS in EC cells stimulated the polarization of M2 macrophages and angiogenesis through secreting SPP1 enriched exosomes." (PMID 38956502, 2024). "Therefore, reducing the infiltration of DAB2+ TAMs or SPP1+ TAMs at the tumor border and blocking their cellular communication with FAP+ CAFs may be another way to enhance anti-tumor immunity." (PMID 39239526, 2024). "Moreover, ligands implicated in the interaction between THBD+ macrophages and malignant tumour cells were identified, including SPP1‐(ITGAV+ITGB1) and APP‐CD74, suggesting the potential of THBD+ macrophages to influence malignant tumour cells through diverse ligands." (PMID 38809929, 2024). "Moreover, pathway analysis revealed that SPP1+APOE+ TAM were regulated by the HIF-1 signaling pathway, inducing expression of VEGFA, LDHA, and ALDOA46,47, which not only promotes hypoxia but is another approach to induce EMT in tumor cells." (PMID 39075108, 2024). "Notably, in LUAD No. 14, macrophages with high SPP1 expression increased in a region characterized by de-differentiated and invasive tumor cells with acinar and solid histological patterns." (PMID 39639005, 2024). "In addition, SPP1 mRNA overexpression positively correlated with epithelioid histology (p = 0.007), higher tumor grade (p = 0.0023), non-head and neck location (p = 0.0576), and poorer overall survival outcomes (HR 1.84, 95% CI 1.07–3.18, p = 0.0288)." (PMID 39409192, 2024). "Our findings that both SPP1 and CCL13, along with their respective interaction, are up‐regulated in F13A1+ Mφs indicate their involvement in shaping the immunosuppressive TME, facilitating tumour immune escape and promoting tumour proliferation and invasion in MPLC." (PMID 39601163, 2024). "However, they did not distinguish which subpopulation of CAFs strongly interacted with SPP1+ macrophages, nor did they take tumor stage into consideration." (PMID 38519500, 2024). "The potential angiogenic effect of SPP1+ macrophage and its potential interaction with tumor cells (SPP1‐CD44) in the triad‐structure area leads to the formation of an environment favorable for ICC tumor growth in leading edge, thus forming a positive feedback loop." (PMID 39716897, 2024). "Therefore, this raised a possibility that TAM-secreted SPP1 activated these pathways such as the JAK-STAT and PI3K-Akt signaling pathways, reduced focal adhesion protein and induced PDL1 expression in epithelial cells to contribute to tumor prognosis." (PMID 38648200, 2024). "RNA-seq analysis of SPP1-stimulated murine neutrophils revealed that these cells could not be classified into classic anti-tumor N1-like or pro-tumor N2-like neutrophils." (PMID 39529085, 2024). "Since SPP1 has been reported to promote tumor cell migration, wound healing and Transwell migration assays were performed to explore whether SPP1 + Macs exerted a similar effect on HNSCC tumor cells." (PMID 39726047, 2024). "Moreover, recent spatial transcriptomic analysis has revealed the direct interaction between CAFs and SPP1 + macrophages through a receptor-ligand network, thereby remodeling the ECM and forming a tumor immune barrier around HCC, which hinders the infiltration of immune cells." (PMID 38679698, 2024). "Moreover, within SPP1 + macrophage population, SIRPα positive cells were found to be closer to tumor cells than SIRPα negative cells." (PMID 39696410, 2024). "Moreover, SPP1 + Mac-derived TNF-α and IL-1β can promote the expression of OPN in both tumor cells and adjacent normal macrophages in turn, which may transform into SPP1 + Macs." (PMID 39726047, 2024). "Therefore, SPP1 is critical for the effects of B4GALNT1 on the polarization and recruitment of M2 macrophages and Th2 cells, which eventually leads to immune escape and tumor progression in HCC." (PMID 39616302, 2024).
tumor (continued). "Our IF assay also suggested that SPP1+ TAMs could be found in tumor regions rather than in adjacent normal tissues, indicating their potential tumor-promoting function in patients with GC." (PMID 39323622, 2024). "In conclusion, CD44 may interact with SPP1, and SLC9A1 to promote certain tumor progression." (PMID 37316699, 2023). "However, it primarily focused on the evolution of tumor cells and did not study the change of TAMs affected by the activation of SPP1/CD44 signaling." (PMID 37194413, 2023). "We speculated that Macro-SPP1 is a critical cellular composition in the tumor boundary, but other subtypes of macrophages were not consistently enriched in malignant or non-malignant regions." (PMID 36806082, 2023). "In contrast, the SPP1+ state is positively correlated with the proportion of Treg, SLEC and NKT cell, and negatively correlated with the proportion of Tn/Tm, Teff/Tem, NK cell and cycling T cells, consistent with a role for SPP1+ macrophages, and Osteopontin itself, in tumor immunosuppression." (PMID 38036590, 2023). "Various genes that were significantly changed, such as CD79B, CLDN2, SPP1 and IGHG3 were the marker genes of the identified cell types or sub-populations, probably owing to the high heterogeneity in cellular compositions across the tumor samples, as observed above." (PMID 37488117, 2023). "SPP1 was not activated by Fam50a or E-cadherin in Runx2-expressing tumor cells." (PMID 37150786, 2023). "SPP1+ TAMs exhibit enriched gene signatures involved in Wnt signaling pathway and support tumor growth while CXCL5+ TAMs enriched in angiogenesis pathways, indicating that TAMs might promote tumor vasculature to facilitate tumor metastasis." (PMID 37936694, 2023). "Furthermore, a protein–protein interaction analysis obtained from the STRING website showed a direct interaction between SPP1 and CD44, MMP3, MMP7, TIMP1 and fibronectin-1, all of which are directly involved in the extracellular matrix remodeling and promotion of tumor metastasis." (PMID 38067407, 2023). "Moreover, the expression levels of KPNA2, PFKFB4, and SPP1 in HCC tumour tissues were significantly higher than those in adjacent normal tissues." (PMID 36873244, 2023). "Interestingly, this cluster of macrophages also highly expressed previously reported tumor associated macrophage (TAM) related genes, including SLC40A1, although a well-defined TAM marker SPP1 was not expressed in Mono-like MAC." (PMID 37957625, 2023). "Furthermore, our finding on the immune microenvironment involved in SPP1 gene regulation allows us to make a conclusion that the upregulation of the SPP1 expression in PSCC enhances the immune response mediated by T cell regulatory Tregs and tumor-infiltrating lymphocytes." (PMID 38111044, 2023). "In addition, we analyzed the gene expression profile of GSE85841 that included eight LUAD samples and adjacent non-tumor samples with adjusted P < 0.05 and logFC≥1.5, and researched the top five most significantly upregulated genes: SFRP5, CST2, SPP1, GCNT3, and NHLRC1." (PMID 35399076, 2022). "We found that both giving STAT3 inhibitor or SPP1‐knockdown could decrease the tumor volume and tumor weight compared to the negative control group, which was more obvious after radiation." (PMID 35593388, 2022). "Notably, SPP1 was more highly expressed on TAMs infiltrating the tumor than on macrophages in non-tumor areas around the tumor." (PMID 36139536, 2022). "Importantly, SPP1+ macrophages are tumor-specific macrophages, accounting for 11.6% of myeloid cells in tumor samples but only 0.68% of the myeloid cells in adjacent normal tissues." (PMID 35365629, 2022). "Secreted phosphoprotein 1 (SPP1, OPN, osteopontin) is an integrin-binding matricellular protein that is involved in a number of physiological and pathological processes, including cell adhesion and migration, angiogenesis, host immune response, wound healing, neurodevelopment, and tumor metastasis." (PMID 34209679, 2021).
tumor (continued). "Importantly, using qRT-PCR, we could validate the higher mRNA expression of the selected genes based our bioinformatics analysis; most selected genes, except SPP1 and FN1, were upregulated in tumor tissue." (PMID 34126961, 2021). "However, the correlation between SPP1 and tumor lymph node metastasis has not yet been investigated." (PMID 34646827, 2021). "These common mutant genes could not explain the function of SPP1 since they had a barely significant effect on prognosis and tumor progression." (PMID 33324676, 2020). "Although HCC cells are not derived from cytokeratin 19 (Krt19) or osteopontin (Spp1) expressing biliary epithelial cells, they express higher levels of Prom1 compared to non-tumor tissues, suggesting the contribution of hepatocyte-derived PROM1+ cells in HCC formation." (PMID 33173221, 2020). "Some studies also showed that SPP1 contributed to tumor cell migration, invasion and survival through PI3K-Akt and STAT3 signaling, and could also promote tumor growth and metastasis by inducing angiogenesis." (PMID 33240930, 2020). "SPP1 (secreted phosphoprotein 1), also known as osteopontin (OPN), was originally described in bone tissue; however, its expression was also described in different cancers, including ovarian, as a protein involved in tumor progression, metastasis, and drug resistance." (PMID 32283808, 2020). "Reduced OPN levels in tumour tissue after the administration of calcitriol or its analogues were rather unexpected because the OPN gene (Spp1) contains a vitamin D response element (VDRE) in the promoter region, whereby calcitriol stimulates various cells to secrete OPN." (PMID 31595196, 2019). "Also known as secreted phosphoprotein 1 (SPP1), OPN is a cytokine involved in many physiological and pathological processes including cell adhesion, angiogenesis, apoptosis, chemotaxis and tumor metastasis." (PMID 31461896, 2019). "In addition, in a recent study using SPP1−/− mice along with gene silencing in tumor cells, OPN produced by tumor cells supported their survival in the blood stream, whereas both tumor- and host-derived OPN, particularly from myeloid cells, rendered the metastatic site more immunosuppressive." (PMID 28193231, 2017). "Indeed, among the enzymes that degrade S1P, the expression of SPL mRNA but not SPP1 mRNA was increased in HCC tissues compared with non-tumorous tissues." (PMID 26886371, 2016). "Nevertheless we can confirm 6 of their identified genes (SPP1, TOP2A, AREG, EGR1, CD34, and IGF1) as well as one of the identified miRNAs (hsa-miR-101), that they found to be differentially expressed in lymph node metastases compared to primary tumours and to normal tissue." (PMID 26537449, 2015). "Though our analysis focused primarily on LEF1 and SPP1, other highly-ranked signature genes with increased expression in CLM compared to primary CRC also have biological functions consistent with roles in tumor progression, and might have prognostic utility." (PMID 21383983, 2011). "Moreover, when SPP1 influences the production of an immunosuppressive TME by CAFs, it inhibits T cell proliferation and activation, recruits regulatory T cells (Tregs) and myeloid-derived suppressor cells (MDSCs), and reduces the effectiveness of the host’s anti-tumor immune response." (PMID 41391064, 2025). "Notably, SPP1+TAMs had similar origins to S100A8+monocytes, and BEAM analysis demonstrated that SPP1, CCLs, and CXCLs co-varied with pseudotime, suggesting that S100A8+monocytes recruited by tumor-derived chemokines can reprogram into SPP1+TAMs and perform pro-tumorigenesis functions." (PMID 39323622, 2024). "However, interactions involving TAMs signalling to malignant cells expressing CD44 via SPP1 and MIF, known to suppress T‐cell activation and promote TAM secretion of growth factors respectively, decreased after therapy, suggesting a transformation towards an anti‐tumour microenvironment." (PMID 39415331, 2024).